TTTY9B (testis expressed transcript, Y-linked 9B)
Synonyms: NCRNA00132; TTTY9; TTTY9A; TTY9
Gene: Long non-coding RNA gene on chromosome Y (18,581,206 to 18,598,111, reverse strand). Ensembl gene ENSG00000131007.
Homologues: Paralogues in human: TTTY9A (100% identical).